SEMA3A (semaphorin 3A)
Diseases named in the same sentence as SEMA3A in open-access papers (continued):
Sharing a sentence is not in itself a finding about the gene and the disease.
neuroblastoma (5 papers, 2015 to 2024). Neuroblastoma (NB) is the most common solid, extracranial childhood tumor. "In addition, recent studies revealed a role of IGF2BP1 in promoting neuroblastoma metastasis via extracellular vesicles guiding SEMA3A and SHMT2 expression." (PMID 37246217, 2023). "In this paper, we examine the role of RhoA and Cdc42 in NG108-15 neuroblastoma cells and we show that they are both involved in Sema3A morphological changes with specific spatio-temporal dynamics; we also show that Cdc42 (but not RhoA) exhibits a complex wave behavior." (PMID 26379503, 2015). "In our experiments, Sema3A local delivery leads to a rapid GC collapse and retraction in NG108-15 neuroblastoma cell line in agreement with similar experiments in DRG neurons." (PMID 26379503, 2015).
Ventricular arrhythmia (5 papers, 2013 to 2023). "We observed the effect of Sema3a overexpression in the MI border zone on the susceptibility to ventricular arrhythmias in a rat MI model." (PMID 23711091, 2013). "Interestingly, prior work had revealed that both deletion and overexpression of Sema3a can cause ventricular arrhythmias and sudden death in mutant mice." (PMID 38235058, 2023). "Cardiac-specific overexpression of SEMA3A increases the risk of death from ventricular arrhythmia due to a marked decrease in intramyocardial cardiac sympathetic nerve fibers, increased catecholamine sensitivity, and prolonged myocardial action potential duration." (PMID 37291626, 2023). "In a mice transgenic model, overexpression of Sema3a in the heart resulted in both reduced sympathetic innervation and increased susceptibility to ventricular arrhythmias as a result of catecholamine supersensitivity and prolongation of the action potential duration." (PMID 23711091, 2013). "It remains unknown now whether local overexpression Sema3a in the MI border zone may decrease or increase the susceptibility to ventricular arrhythmias." (PMID 23711091, 2013). "Overexpression of SEMA3A in the myocardium reduces ventricular arrhythmias by downregulating sympathetic reinnervation in the rat MI model." (PMID 37291626, 2023). "Myocardial overexpression of Sema3a after infarction can reduce the inducibility of ventricular arrhythmias as a result of attenuated sympathetic reinnervation." (PMID 23711091, 2013). "Overexpression of Sema3a in MI border zone could reduce the inducibility of ventricular arrhythmias by reducing sympathetic hyper-reinnervation after infarction." (PMID 23711091, 2013). "Overexpression of vascular endothelial growth factor-β (VEGF-β) in myocardium, which competes with SEMA3A for binding to NRP1, promotes ventricular arrhythmias due to enhanced sympathetic nerve sprouting in the myocardium." (PMID 37291626, 2023). "Importantly, we found cardiac nerve injury caused by MI could not significantly trigger the reexpression of sema3A, but overexpression of sema3A in MI border zone could reduce sympathetic hyperreinnervation accompanied by reduced inducibility of ventricular arrhythmias." (PMID 26793403, 2015).
apical periodontitis (4 papers, 2017 to 2022). "Combined with our results, it is highly likely that the reduction in Sema3A/Nrp1 expression was involved in the occurrence and developmental process of bone loss in apical periodontitis." (PMID 29457037, 2017). "We detected the expression patterns of Sema3A/Nrp1 at different developmental stages and their association with bone destruction in a rat model of apical periodontitis." (PMID 29457037, 2017). "In this study, we firstly investigated the expression pattern of Sema3A/Nrp1 in apical periodontitis and its correlation with bone destruction." (PMID 29457037, 2017). "The clinical samples obtained from apical periodontitis patients also demonstrated downregulated expression levels of Sema3A and Nrp1 in apical periodontitis compared to healthy control." (PMID 29457037, 2017). "In apical periodontitis, the expression of Sema3A is decreased, along with the reduced binding of Sema3A and Nrp1." (PMID 29457037, 2017). "This study demonstrated that Sema3A/Nrp1 expression was significantly decreased in rat apical periodontitis models as well as in apical periodontitis patients." (PMID 29457037, 2017). "In our study, the expression levels of Sema3A and Nrp1 were remarkably decreased in induced rat apical periodontitis as the disease progressed." (PMID 29457037, 2017). "Accumulating evidence has encouraged investigations on the potential roles of Sema3A/Nrp1 in apical periodontitis." (PMID 29457037, 2017). "Moreover, a decline in the expression of SEMA3A/NRP-1 signaling has been reported earlier in rats with periapical lesions as well as patients with apical periodontitis." (PMID 34821196, 2021). "The reduction in Sema3A/Nrp1 expression may have a suppressive effect on the pathological severity of apical periodontitis by inhibiting osteoblasts, activating osteoclasts, and enhancing inflammation." (PMID 29457037, 2017). "In addition, clinical samples from apical periodontitis patients were obtained to analyse the expression of Sema3A/Nrp1." (PMID 29457037, 2017). "In this study, we hypothesized that the Sema3A/Nrp1 signaling axis would significantly contribute to bone resorption in apical periodontitis." (PMID 29457037, 2017). "Further elucidation of the role of Sema3A/Nrp1 in this disease may address the biological and pathological functions of Sema3A/Nrp1 and allow the development of new strategies for the treatment of apical periodontitis." (PMID 29457037, 2017). "In conclusion, decreased expression of Sema3A/Nrp1 was observed in periapical lesions and is potentially involved in the bone resorption of the periapical area, suggesting that Sema3A/Nrp1 may contribute to the pathological development of apical periodontitis." (PMID 29457037, 2017). "Moreover, the imbalance in Sema3A and Nrp1 may also affect the etiology of apical periodontitis." (PMID 29457037, 2017). "In addition, we found that Sema3A/Nrp1 expression exhibits a significantly negative correlation with osteoclast formation in apical periodontitis." (PMID 29457037, 2017).
breast tumor (4 papers, 2012 to 2020). "These research evidences suggested that Sema3A may serve as a candidate tumor suppressor that attenuates breast tumor progression." (PMID 31929841, 2019).
cervical carcinoma (4 papers, 2014 to 2021). A carcinoma arising from either the exocervical squamous epithelium or the endocervical glandular epithelium. "In fact, Sema3A was found to overcome drug resistance in pancreatic neuroendocrine tumors and cervical cancer to the small molecule tyrosine inhibitor imatinib." (PMID 28683823, 2017). "We showed here that Semaphorin 3A relies on KIAA1199 to transiently trigger EGFR phosphorylation in cervical cancer cells." (PMID 25366117, 2014). "We showed here that KIAA1199 protects from cell death triggered by Semaphorin 3A or by TNFα in cervical cancer cells." (PMID 25366117, 2014). "Therefore, KIAA1199 protects cells from Semaphorin 3A- and Plexin A2-dependent cell death in cervical cancer-derived cells." (PMID 25366117, 2014). "As Plexin A2 deficiency enhanced Semaphorin 3A-dependent EGFR phosphorylations and also increased KIAA1199 protein levels, KIAA1199 acts as a pro-survival protein, at least by promoting EGFR signalling to limit Semaphorin 3A- and Plexin A2-mediated cell death in cervical cancer cells." (PMID 25366117, 2014). "Therefore, KIAA1199 protects cervical cancer cells from Semaphorin 3A-mediated cell death." (PMID 25366117, 2014). "One may indeed expect KIAA1199 to directly interfere with pro-apoptotic, Plexin A2-dependent cascades as we demonstrated an additive effect between Semaphorin 3A and EGFR inhibition in triggering apoptosis in cervical cancer cells." (PMID 25366117, 2014). "Therefore, KIAA1199 connects Semaphorin 3A signalling to EGFR phosphorylation and maintains high EGFR levels in cervical cancer-derived cells." (PMID 25366117, 2014).
colon cancer (4 papers, 2017 to 2022). "HGF from cultured myogenic cells may have influenced the differential responses by endothelial and myogenic cells to Sema3A and 3F, as found in studies of human colon cancer in a mouse transgenic strain." (PMID 29854302, 2018).
colorectal cancer (4 papers, 2019 to 2023). A primary or metastatic malignant neoplasm that affects the colon or rectum. "Nanobodies (Nbs) targeting NRP-1 were generated for their potential to hamper the NRP-1/Sema3A interaction and their impact on colorectal carcinoma (CRC) development was evaluated in vivo through the generation of anti-NRP-1-producing CRC cells." (PMID 33266104, 2020). "In addition, the expression levels of neuropilin 1 and neuropilin 2, receptors for Sema3A, and Neogenin and deleted in colorectal cancer (DCC), receptors for Netrin-1, were evaluated by RT-qPCR." (PMID 36986209, 2023).
glomerular disease (4 papers, 2015 to 2024). "Since excess SEMA3A has been reported to be associated with various glomerular diseases, we applied the Dox-induced podocytopathy mouse model and examined the change of SEMA3A expression." (PMID 32521824, 2020). "It was also shown that an overexpression of Sema3a in podocytes in vivo was associated with glomerular disease, via deregulation of the nephrin/Plexin-A1 interaction thus linking Sema3A and Plexin-A1 to SD complexes." (PMID 26239560, 2015). "Previous studies have shown increased Sema3A expression in various glomerulopathies, indicating a gap in understanding its role." (PMID 39301490, 2024). "For example, SEMA3A expression is increased in various glomerular diseases." (PMID 32521824, 2020).
inflammatory bowel disease (4 papers, 2015 to 2023). A spectrum of small and large bowel inflammatory diseases of unknown etiology. "Sema3A expression levels in CD4+/CD25+ T cells were significantly lower in patients with inflammatory bowel diseases than in controls, although their serum Sema3A levels were significantly higher." (PMID 30538782, 2018). "Altered % of Tregs expressing sema3A in patients with inflammatory bowel diseases (IBD) is partially responsible for their failure in preventing CD4+ effector T cell induced inflammation in IBD in peripheral blood." (PMID 25978359, 2015).
ischemia (4 papers, 2015 to 2022). A hypoperfusion of the BLOOD through an organ or tissue caused by a PATHOLOGIC CONSTRICTION or obstruction of its BLOOD VESSELS, or an absence of BLOOD CIRCULATION. "Like Sema3A, Sema6A also plays an important role in cortical neuronal networks rewiring after ischemia." (PMID 35350431, 2022). "Sema3A reduces cardiac inflammation by regulating cardiac monocyte/macrophage function in response to ischemia-induced myocardial injury." (PMID 29849491, 2018). "We further addressed the effect of Sema3A on macrophage function, as timely resolution of cardiac inflammation is a vital step in proper cardiac healing in response to ischemia." (PMID 28540528, 2017). "In addition, Increasing IL-1β, released by microglial cells in ischemia, induces microvascular injury through the release of Sema3A from adjacent neurons and it can be reversed by knockdown of Sema3A." (PMID 35350431, 2022).
ischemic stroke (4 papers, 2020 to 2024). A stroke disorder caused by obstruction of blood flow to the brain, due to thrombotic (local blood clot formation) or embolic (due to a blood clot or other material traveling from another site) event. "miR-122-5p and miR-145-5p are involved in the pathological process of ischemic stroke through the targeting of Nurrl and SEMA3A, as previously reported." (PMID 36203804, 2022). "In this study, we mainly illustrated a mechanism of MEG3/miR-424-5p/Sema3A axis mediating ischemic stroke." (PMID 32065781, 2020). "Sema3A/NRP signal pathway can activate glial cells to exert phagocytosis which induces neuron apoptosis and participates in glial scar formation in ischemic stroke." (PMID 35350431, 2022).
leukemia (4 papers, 2015 to 2022). A malignant (clonal) hematologic disorder, involving hematopoietic stem cells and characterized by the presence of primitive or atypical myeloid or lymphoid cells in the bone marrow and the blood. "Evidence from normal skin cells has proven that SEMA3A knockdown enhances radiation resistance, suggesting an increased radiosensitivity with loss-of-silencing on SEMA3A in leukemia." (PMID 26043758, 2015). "Sema3A and Sema4D were furthermore similarly implicated in leukemia cell regulation." (PMID 33537086, 2021). "However, in the leukemia cell line, a peak with both EZH2 and H3K27me3 enrichment has not been observed in the human genomic region within 150kbp distance to SEMA3A, suggesting a leukemia-specific loss of EZH2-silencing on SEMA3A." (PMID 26043758, 2015). "We observed the loss of EZH2 and H3K27me3 enrichment on the SEMA3A promoter in leukemia and hypothesized that this loss rescues SEMA3A expression and facilitates leukemogenesis after chemo- or radiotherapy." (PMID 26043758, 2015). "In an independent study, SEMA3A was also found to induce apoptosis in leukemia cells, via NRP1 co-receptor." (PMID 31143707, 2019). "Noteworthy, current data support a promoting role for Semaphorin 4D and Neuropilin-1 in these tumors, while Semaphorin 3A seems to consistently act as oncosuppressor in leukemias and multiple myeloma." (PMID 31143707, 2019). "Consistent with the posited tumor suppressor role of this semaphorin, experimental studies ex vivo have shown that Sema3A can suppress the growth and promote the apoptosis of human leukemic cells, via diverse mechanisms; Sema4D, in contrast, was found to promote leukemia cell survival and growth." (PMID 33537086, 2021). "However, Yang Zhi-Gang has reported that Sema3A was downregulated in acute leukemia, and exogenous Sema3A could inhibit the Nrp-1 expression on Tregs and promote apoptosis in leukemia cells." (PMID 35155237, 2022).
psoriasis (4 papers, 2018 to 2026). An autoimmune condition characterized by red, well-delineated plaques with silvery scales that are usually on the extensor surfaces and scalp. "Repression of miR-142-3p leads to increased expression of the Sema3A gene, and this, in turn, alleviates psoriasis-like inflammation by inhibiting proliferation and promoting apoptosis of keratinocytes." (PMID 38139064, 2023). "In turn, the significant role of Treg is also supported by the fact that after phototherapy, along with an improvement in skin condition, the function of Treg cells improves, confirming the defective function of Sema3A/Treg in psoriasis-affected skin." (PMID 38139064, 2023). "Several studies indicate a relationship between Sema3A expression and pruritic sensitization in psoriasis." (PMID 38139064, 2023). "A final important aspect of Sema3A function in the pathogenesis of psoriasis, as in other pruritic diseases, is its effect on nerve fiber growth and pruritus sensation." (PMID 38139064, 2023). "Sema3A levels were significantly higher in moderately ill and overweight patients (p < 0.05, p < 0.01, respectively) and in patients with longer-lasting psoriasis and male patients compared to controls (both p < 0.05)." (PMID 41893339, 2026). "It is suspected that reduced expression of Sema3A in keratinocytes of psoriasis patients may be involved in the development of pruritus." (PMID 38139064, 2023). "It is thought that Sema3A may play a significant role in psoriasis by affecting keratinocyte proliferation and VEGF, as it does in cancer cells." (PMID 38139064, 2023). "Sema3A expression has been shown to decrease in the epidermis of psoriasis patients." (PMID 38139064, 2023). "In patients with psoriasis and AD, there is an increase in the expression of amphiregulin and NGF and a decrease in the expression of Sema3A in the epidermis compared to the control group." (PMID 38139064, 2023). "Expression levels in the epidermis of Sema3A tended to decrease in psoriasis patients; however, the results were also not statistically significant." (PMID 38139064, 2023). "Both the intensity of pruritus and the clinical concerns of psoriasis show a negative correlation with Sema3A mRNA expression." (PMID 38139064, 2023). "In many studies, both the intensity of pruritus and the clinical manifestations of psoriasis show a negative correlation with Sema3A mRNA expression." (PMID 38139064, 2023). "However, not all studies support the correlation of Sema3A with nerve fiber density in patients with psoriasis and pruritus." (PMID 38139064, 2023). "The possibility of applying Sema3A to treat severe psoriasis when biological treatment fails to produce the desired results may prove to be a new therapeutic tool." (PMID 38139064, 2023).
systemic sclerosis (4 papers, 2018 to 2023). A chronic disorder, possibly autoimmune, marked by excessive production of collagen which results in hardening and thickening of body tissues. "Quantitative analysis of Sema3A expression in patients with systemic sclerosis (SSc) showed lower serum levels of Sema3A as compared to healthy controls and patients with diagnosed SLE." (PMID 30134791, 2018).
tongue squamous cell carcinoma (4 papers, 2012 to 2025). A squamous cell carcinoma that arises from the tongue. "It has been observed that overexpression of SEMA3A in the tongue squamous cell carcinoma cell line SSC-9 result in suppressed tumor growth in mice and inhibition of VEGFR2, Src and FAK phosphorylation." (PMID 29649113, 2018). "In this study, we focused on the most common type of oral cancer, tongue squamous cell carcinoma, and examined the expression of SEMA3A and NRP1." (PMID 22926477, 2012). "In addition, overexpression of Sema3A in the tongue squamous cell carcinoma cell line SSC-9 resulted in significantly reduced angiogenesis and drastically suppressed tumor growth in mice." (PMID 28683823, 2017). "In contrast, overexpression of SEMA3A correlated with inhibition of Src and FAK (focal adhesion kinase) kinases phosphorylation in tongue squamous cell carcinoma cell line SSC-9." (PMID 41465532, 2025). "However, the role of SEMA3A in tongue squamous cell carcinoma remains unclear." (PMID 22926477, 2012).
atherosclerosis (3 papers, 2018 to 2026). A disease characterized by the build-up of fatty material and calcium deposition in the arterial wall resulting in partial or complete occlusion of the arterial lumen. "Like Sema4A, Sema4D, Sema3A, and Sema7A, reported to participate in atherosclerosis, are also widely investigated in immune cells." (PMID 30405423, 2018). "Similar to Sema3A, netrin-1 was found to be involved in the initiation of atherosclerosis." (PMID 30405423, 2018).
autism (3 papers, 2009 to 2024). Persistent deficits in social interaction and communication and interaction as well as a markedly restricted repertoire of activity and interest as well as repetitive patterns of behavior. "Additional signaling networks that are also implicated in social behavioral deficits in autism include AVB3-INTEGRIN, PI3K-ERBB2/4, SEMA3A-PKA, and REELIN signaling." (PMID 31827489, 2019). "Additional signaling networks of potential importance in autism social behavioral deficits include AVB3-integrin (n = 7 genes), PI3K-ERBB2/4 (n = 4 genes), Sema3A-PKA (n = 3 genes), and Reelin (n = 3 genes)." (PMID 31827489, 2019).